SCAND3 (SCAN domain containing 3)
Synonyms: Buster4; KIAA1925; ZBED9; ZNF305P2; ZNF452; ZFP38-L; FLJ31087; FAM200D; dJ1186N24.3
Tractability: No criterion of Open Targets' tractability assessment is met for any kind of drug.
Gene: Protein-coding gene on chromosome 6 (28,570,535 to 28,616,212, reverse strand). Ensembl gene ENSG00000232040.
Subcellular location: Nucleus
Subcellular location (Human Protein Atlas): Nucleoli; Golgi apparatus; Nucleoplasm
Gene Ontology:
Molecular function: nucleic acid binding
Biological process: positive regulation of cell cycle; positive regulation of epithelial cell proliferation; DNA integration
Cellular component: cytoplasm; nucleus
Genetic constraint (gnomAD): Loss-of-function variants: 52 observed, 110.6 expected, observed/expected ratio (o/e) 0.47, 90% interval 0.38 to 0.59. The synonymous counts are far from expectation, so gnomAD's model fits this gene poorly and the ratio says little. Missense variants: 1,224 observed, 1,622.4 expected, observed/expected ratio (o/e) 0.75, 90% interval 0.72 to 0.79. Synonymous variants: 451 observed, 565.53 expected, observed/expected ratio (o/e) 0.8, 90% interval 0.74 to 0.86.
Homologues: Orthologues: chimpanzee SCAND3 (99% identical), macaque SCAND3 (98% identical), pig SCAND3 (89% identical), dog SCAND3 (85% identical), rat Zbed5 (20% identical), mouse Zbed5 (19% identical). Paralogues in human: ZBED5 (18% identical), ZBED11 (17% identical), ZBED8L (16% identical), ZBED8 (14% identical), EPM2AIP1 (10% identical), ZMYM4 (6% identical), THAP12 (6% identical), ZMYM2 (6% identical), ZMYM3 (5% identical), GTF2IRD1 (5% identical), ZMYM6 (5% identical), ZMYM1 (4% identical), and 6 more.
Diseases named in the same sentence as SCAND3 in open-access papers:
SCAND3 is named in the same sentence as 14 diseases in open-access papers, as found by Europe PMC text mining. Sharing a sentence is not in itself a finding about the gene and the disease. The quoted sentences say what the papers report.
hepatocellular carcinoma (3 papers, 2020 to 2025). A malignant tumor that arises from hepatocytes. "Our research is aimed at identifying and validating effective noninvasive biomarkers for HCC management, and our previously published study has indicated that hypermethylation of SCAND3 and Myo1g gene was a potential diagnostic biomarker for hepatocellular carcinoma." (PMID 33628341, 2021).
tumor (5 papers, 2015 to 2025). "Furthermore, we observed that the SCAND3 methylation status was associated with portal vein tumor thrombus in HCC patients, which indicated its potential usefulness as a predictor for HCC progression." (PMID 32824823, 2020). "The hypermethylation of SCAND3 was significantly correlated with the tumor size (χ2 = 4.595, p = 0.032) and portal vein tumor thrombus (χ2 = 8.967, p = 0.003)." (PMID 32824823, 2020).
cancer (4 papers, 2015 to 2025). A tumor composed of atypical neoplastic, often pleomorphic cells that invade other tissues. "Consequently, we conducted a pan-cancer analysis of gene promoter methylation and observed significant associations between several genes, including ZNF323, ZSCAN23, SCAND3, PRSS16, ZNF391, NKAPL, and ZNF311, and promoter methylation." (PMID 38495498, 2024). "It should be noted that only SCAND3 methylation was found to be associated with early-stage HCC recurrence, and Myo1g has been not investigated previously in respect to human cancers." (PMID 32824823, 2020).
SCAND3 also shares sentences with these, for which no sentence is quoted: asthma (1 paper); cancer of the liver (1); cardiovascular diseases (1); Hypertension (1); liver cirrhosis (1); lung adenocarcinoma (1); lung carcinoma (1); lymph node metastasis (1); mild cognitive impairment (1); non-small cell lung carcinoma (1); squamous cell carcinoma (1).